ANXA1 (annexin A1)
Diseases named in the same sentence as ANXA1 in open-access papers (continued):
Sharing a sentence is not in itself a finding about the gene and the disease.
lung carcinoma (continued). "The results showed that among the six lung cancer cell lines, all cell lines (A549, H460, H1650, H1975, H157, PC9 and H1703) expressed ANXA1 at levels substantially higher than those expressed by normal human fetal lung fibroblast cells (WI-38)." (PMID 34439260, 2021). "Western blotting analysis of 10K and 100K pellets in lung cancer cell lines was based on CD9 and CD63 as markers of small EVs (exosomes), and BiP and Annexin A1 as markers of large EVs (oncosomes)." (PMID 32634139, 2020). "The changes in the down-stream signaling pathways of EGFR in lung cancer cells with and without ANXA1 knockdown or Osimertinib treatment were then studied." (PMID 34439260, 2021). "Moreover, Hsp90-beta and annexin A1 were highly expressed in stages III (82% and 68%) and IV (100% and 75%) compared with stages I (both 0%) and II (45.3% and 32.1%) of lung cancer tissues (p < 0.05)." (PMID 22929401, 2012). "Overall, these data indicate that the anti-proliferative effect of MDX-124 is associated with ANXA1 expression, as cell lines responsive to MDX-124 treatment all expressed ANXA1, whereas a non-expressing lung cancer cell line (COR-L23) exhibited no response to MDX-124." (PMID 38200229, 2024). "Similarly, in lung cancer, the overexpression of ANXA8 activates the EGFR/AKT/mTOR signalling pathway to promote proliferation, while in thyroid cancer, increased ANXA1 promotes thyroid cancer proliferation by mediating IL-6/JAK2/STAT3." (PMID 36936694, 2023). "This has been analysed in hepatocellular carcinoma, colorectal carcinoma and lung cancer whereby treatment to respective cell lines of HepG2 by Sorafenib, HCT116 by Indomethacin and A549 cells by Eurycomanone resulted in significant down-regulation of ANXA1 protein expression." (PMID 29614751, 2018). "In addition, to further investigate the role of ANXA1 in IAV-induced autophagy flux, chloroquine (CQ) was used to treat the A549 and A549-ΔANXA1 lung cancer cells with or without IAV infection." (PMID 32512864, 2020).
pancreatic cancer (51 papers, 2008 to 2026). "While in lung adenocarcinoma, gastric cancer, hepatocellular carcinoma, melanoma, and pancreatic cancer, ANXA1 is upregulated and associated with poor prognosis." (PMID 34991599, 2022). "Annexin A1 (ANXA1) has also been documented to play an important role in inward vesiculation and its suppression was associated with reduced exosome secretion in pancreatic cancer cells." (PMID 34078376, 2021). "Annexin A1 (ANXA1), a 37 kDa multifunctional protein, is over-expressed in tissues from patients of pancreatic carcinoma (PC) where the protein seems to be associated with malignant transformation and poor prognosis." (PMID 25510623, 2014). "However, another research suggested that ANXA1 associated with NF‐kappaB and suppressed its transcriptional activity by preventing NF‐kappaB binding to DNA in colon and pancreatic cancers." (PMID 35770335, 2022). "Annexin A1 (ANXA1) is associated with malignant features of pancreatic cancer." (PMID 32756339, 2020). "On the other hand, increased expression pattern of ANXA1 in hepatocellular carcinoma, colorectal cancer, and pancreatic cancer was shown to be associated with tumor growth, lymph node metastasis, and advanced disease stages, and consequently with poor patient outcome." (PMID 25038797, 2014). "Although expression of Annexin A1 was reported to be associated with a number of cancers including pancreatic cancer, the molecular mechanism underlying is unknown." (PMID 23890079, 2013). "ANXA1 high levels on the contrary to BC, melanoma, pancreatic cancer, are low or undetectable in other tumors, e.g., esophageal, head and neck, prostate cancer, oral squamous cell carcinoma, or even show different levels of GlcNAcylation (colorectal cancer)." (PMID 38892394, 2024). "Anxa1 has been shown to trigger angiogenesis such as cell functional migration and invasion in Pancreatic cancer." (PMID 39026350, 2024). "ANXA1 has been analyzed in the extracellular environment once secreted through microvesicles (EVs) by pancreatic cancer (PC) cells." (PMID 34944403, 2021). "Specifically, in this study, we investigated the clinical relevance of ANXA1 expression in pancreatic cancer (PC)." (PMID 33804148, 2021). "Annexin A1 (ANXA1) is a calcium-dependent phospholipid-binding protein overexpressed in pancreatic cancer (PC)." (PMID 33804148, 2021). "The TME in pancreatic cancer (PC) is critical for its aggressiveness and the annexin A1 (ANXA1) has been identified as one of the oncogenic elements." (PMID 34681678, 2021). "It was investigated that the knockdown of ANXA1 diminishes the amounts of secreted EVs, particularly exosomes, in pancreatic cancer cells, indicating that ANXA1 positively regulates exosome biosynthesis." (PMID 32756339, 2020). "In a pancreatic cancer cell line, ANXA1 played a role in preserving the malignant phenotype; it was involved in the potential for migration and invasion." (PMID 31882967, 2019). "The oncogenic role of ANXA1 has been found also in pancreatic cancer (PC), where protein expression directly correlates with patients’ poor prognosis." (PMID 29986379, 2018). "Among the several tumour models where the role of ANXA1 remains controversial, in pancreatic cancer (PC) ANXA1 expression is related to tumour development and drug resistance." (PMID 30518142, 2018). "Annexin A1 (ANXA1) is a Ca2+-binding protein that is involved in pancreatic cancer (PC) progression." (PMID 29986379, 2018). "All methods showed that ANXA1 was down-regulated in esophageal, gastric, and bile duct cancers, but up-regulated in pancreatic cancer." (PMID 25038797, 2014). "Clearly, Annexin A1 is expressed significantly in pancreatic cancer patients compared to the healthy controls (p < 0.05)." (PMID 23890079, 2013). "There was a significant correlation between ANXA1 gene expressed in pancreatic cancer juice and tissue samples when ductal adenocarcinoma samples were analysed as a discrete cohort." (PMID 21245863, 2011).
pancreatic cancer (continued). "The results indicate that ANXA1 in pancreatic ductal juice has translational potential as a marker of pancreatic cancer." (PMID 21245863, 2011). "ANXA1 supports an immunosuppressive TME, promoting M2 polarization represented by TREM2 TAMs mobilization, ANXA1 derived from cancer cells may be involved in the formation of a TME specific to pancreatic cancer." (PMID 41228323, 2025). "Likewise, pancreatic cancer progression and metastasis are promoted by ANXA1 via micro vessel development, cytoskeletal remodeling leading to cell motility, and as an agonist of formyl peptide receptors." (PMID 38892394, 2024). "This suggests that ANXA1-targeted therapy may have utility in tumour types like pancreatic cancer which rely on highly aggressive front-line chemotherapeutic treatment regimens." (PMID 38200229, 2024). "Interestingly, AnxA1 ablation restores the sensitivity of colorectal and pancreatic cancers to chemotherapeutic agents through the inhibition of the drug efflux pump, p-glycoprotein." (PMID 35897832, 2022). "Notably, reduced expression of Annexin A1 has been reported to promote gemcitabine and 5-fluorouracil drug resistance of human pancreatic cancer." (PMID 35203351, 2022). "Indeed, previous studies have revealed that in pancreatic cancer (PC) ANXA1 acts as an intra- and extracellular component promoting the progression." (PMID 34944403, 2021). "In addition, ANXA1 is able to promote cell migration, invasion, and angiogenesis and participate in pancreatic cancer progression." (PMID 34484309, 2021). "Annexin A1 (ANXA1) is a Ca2+-binding protein over-expressed in pancreatic cancer (PC)." (PMID 27412958, 2016). "Nonetheless, a possible novel treatment option for ANXA1 positive, tamoxifen resistant tumors would consist of blocking antibodies, which have already shown efficacy in inhibiting migration and invasion rates in pancreatic carcinoma cells." (PMID 26657294, 2016). "Overexpression of ANXA1 protein is observed in hepatocellular carcinoma and pancreatic cancer." (PMID 25490767, 2014). "In contrast to esophageal carcinoma, ANXA1 mRNA was up-regulated 1.6-fold in pancreatic carcinomas." (PMID 25038797, 2014). "Furthermore, investigation of ANXA1 protein level revealed extremely stronger expression of this protein in pancreatic carcinomas than in the surrounding benign pancreatic tissue (D and 2 second panel)." (PMID 25038797, 2014). "Annexin A1 has been reported to show altered expression in a variety of different cancers, including oesophageal cancer, pancreatic cancer and hairy cell leukaemia." (PMID 18071363, 2008). "Notably, high ANXA1 expression was significantly associated with worse overall survival in the TCGA PDAC cohort, further supporting its potential role as a prognostic biomarker in pancreatic cancer." (PMID 40484878, 2025). "In order to improve the investigation of pancreatic cancer (PC), often supported through analyzes two-dimensional (2D) cell monolayers, we proposed to create a spheroid-based in vitro three-dimensional (3D) model using wild-type (WT) and ANXA1 knock-out (KO) MIA PaCa-2 PC cells." (PMID 36230687, 2022). "A correlation between ANXA1 expression and drug resistance was observed in different tumors where the protein seems to act by inducing the drug resistance behavior in lung adenocarcinoma, pancreatic cancer and ovarian cancer or by reducing it in bladder cancer, hepatoma and myeloid leukemia." (PMID 26312765, 2015). "In pancreatic cancer tissues, ADM, KRT17, and ANXA1 protein levels surpassed those in normal samples, while C7 and ALB protein levels exhibited a declining trend, in accordance with the findings from qRT-PCR and bioinformatics analysis." (PMID 37941546, 2023). "ANXA1 and KRT17 consistently demonstrated expression trends that concurred with our overall bioinformatics analysis in six out of seven pancreatic cancer patients, indicating heightened expression in tumor tissues." (PMID 37941546, 2023).
pancreatic cancer (continued). "Some of them (ITGA3, CDK1, IFIT3, ANXA1, ANXA2, OAS1, and LACTB) have been studied to varying degrees concerning their relationship with pancreatic cancer." (PMID 36834681, 2023). "Moreover, exosomal ANXA1 can promote migration, invasion, and EMT of pancreatic cancer cells, as well as angiogenesis by interaction with HUVECs." (PMID 31355262, 2019). "Thus, the coordinated regulation of ANXA1 and sphingomyelin phosphodiesterase 3 (SMPD3) may promote exosome biogenesis in pancreatic cancer." (PMID 32756339, 2020).
melanoma (42 papers, 2010 to 2025). A malignant, usually aggressive tumor composed of atypical, neoplastic melanocytes. "Previous studies demonstrated that melanoma cells expressed AnxA1 into the microenvironment, which is associated with angiogenesis, tumor cell invasiveness, and growth." (PMID 36766767, 2023). "Furthermore, impaired melanoma lung metastasis in AnxA1-/- mice was associated with the inhibition of angiogenesis, pointing out that AnxA1 is a player protein such as on cancer as stromal cells." (PMID 36766767, 2023). "Additionally, the reduction of lung melanoma metastasis in AnxA1-/- mice was associated with neovascularization impairment." (PMID 36766767, 2023). "Moreover, mechanisms of metastatic invasiveness in melanoma have been associated with the overexpression of annexin A1 in malignant cells." (PMID 35017628, 2022). "For example, Annexin A1 (encoded by ANXA1) is a Ca(2+)-regulated phospholipid-binding protein that is overexpressed in many cancers such as breast, pancreatic, and melanoma, having many roles in the progression of this disease by localizing to different cell compartments." (PMID 31749682, 2019). "Elevated levels of AnxA1 were detected in the biopsies and serum of melanoma patients, alongside increased neutrophil-lymphocyte ratios." (PMID 40636453, 2025). "Inhibition of AnxA1 led to a reduction in both metastasis and AnxA1 levels, suggesting its potential as a biomarker for the progression of melanoma." (PMID 40636453, 2025). "TEXs release from malignant melanoma cells have a high level of expression with annexin A1; however, the expression of annexin A2 was shown to be downregulated." (PMID 40305328, 2025). "In mice with lung melanoma metastasis, neutrophils exhibited higher AnxA1 levels, which facilitated melanoma cell invasion through FPR pathways." (PMID 40636453, 2025). "It was reported that downregulation of ANXA1 inhibited cell migration and proliferation in studies on melanoma progression, consistent with our findings regarding cell senescence." (PMID 38358087, 2024). "Melanoma cells and neutrophils expressing AnxA1 were detected in biopsies from primary melanoma patients, which also presented higher levels of serum AnxA1 and augmented neutrophil–lymphocyte ratio (NLR) in the blood." (PMID 36766767, 2023). "The depletion of peripheral neutrophils during lung melanoma metastasis development (anti-Gr1; i.p. every 48 h for 21 days) reduced the number of metastases and AnxA1 serum levels in mice." (PMID 36766767, 2023). "Further experimental data showed that neutrophils that infiltrated into the melanoma lung metastasis expressed elevated levels of AnxA1 in comparison to melanoma cells." (PMID 36766767, 2023). "Here, high serum AnxA1 levels and neutrophils expressing AnxA1 were consistent, such as that found in melanoma samples from patients as in the melanoma mice model." (PMID 36766767, 2023). "Further, in NCM containing low levels of AnxA1 (lower than 2 ng/mL), the melanoma cell invasion was reduced in comparison to NCM with detectable AnxA1 levels." (PMID 36766767, 2023). "In the third sample, the majority of cell types found in the dermis were melanoma cells, being that almost all of them expressed AnxA1." (PMID 36766767, 2023). "Here, data obtained in melanoma patients corroborate this evidence, as augmented AnxA1 expression in the cytoplasm of cells from a dysplastic nevus and melanoma patients was detected." (PMID 36766767, 2023). "As recruited neutrophils are player cells at the tumor sites, the role of neutrophil-derived AnxA1 in lung melanoma metastasis was investigated here." (PMID 36766767, 2023). "In the dysplastic nevus and first melanoma samples, cells scattered throughout the dermis, as seen by H&E staining, were positive for AnxA1 in both samples." (PMID 36766767, 2023). "The AnxA1 expression was found in melanoma tumor cells and immune cells in the lung from both isotype and neutrophil-depleted mice." (PMID 36766767, 2023).
melanoma (continued). "In vitro studies corroborating the expression of AnxA1 by melanoma cells is related to invasiveness behavior, depending, at least in part, on metalloproteinase-2 (MMP-2) expression." (PMID 36766767, 2023). "On the basis of these previous data, we further investigated the involvement of AnxA1 secreted by neutrophils on melanoma cell invasion." (PMID 36766767, 2023). "The fact that we found an increase in AnxA1 serum levels brings an alternative approach to help in the diagnosis of melanoma, and a large cohort is needed to support the potential of AnxA1 as a biomarker for melanoma detection or progression." (PMID 36766767, 2023). "Our findings added AnxA1 secreted by neutrophils in the blood or at metastasis sites as a new player of the melanoma cell invasion, pointing to AnxA1 as a pivotal mediator secreted by neutrophils acting on cancer cells." (PMID 36766767, 2023). "For example, annexin A1 (upregulated in WM115-derived exosomes) is a known promoter of primary melanoma tumor dissemination, mainly by inhibiting E-cadherin expression." (PMID 36831440, 2023). "On the basis of the expression of AnxA1 in melanoma cells and neutrophils from melanoma patients, a model of lung melanoma metastasis was employed to investigate the pattern of AnxA1 expression and neutrophil infiltration in the metastatic site." (PMID 36766767, 2023). "A previous retrospective clinical study showed that high AnxA1 expression in melanoma cells from primary tumors reduced metastasis-free survival, but AnxA1 expression levels were unchanged according to the Breslow index." (PMID 36766767, 2023). "To the best of our knowledge, we suggest, for the first time, that neutrophils secrete AnxA1 in melanoma metastasis and can influence tumor development." (PMID 36766767, 2023). "In the second melanoma sample, an increased number of pigmented and melanoma cells and AnxA1-positive cells were detected." (PMID 36766767, 2023). "Among them, we found Sparc, Cd47, Plec, Anxa1, Anxa 3, and Anxa 5, genes strongly involved in the metastatic processes of melanoma." (PMID 37898636, 2023). "Others showed that ANXA1 is upregulated in melanoma, hepatocellular carcinoma, gastric cancer and lung adenocarcinoma, which correlates with poor prognosis." (PMID 34200100, 2021). "Dietary fiber-derived short-chain fatty acid butyrate promotes melanoma cell invasion by the induction of Annexin A1 (ANXA1), which negatively regulated E-cadherin expression in an in vitro experiment." (PMID 34069297, 2021). "During the characterization of melanoma cell lines, it was found that an increase in the acidic and basic isoforms of annexin-a1 (AnxA1) was found in A375 as compared to melanocytes and 526 cells." (PMID 34681580, 2021). "AnxA1 has been identified in mouse melanoma cell lines by comparative proteomic studies and appears to enhance melanoma invasion and spread." (PMID 34681580, 2021). "MITF had a positive correlation with its target ANXA1 in lung adenocarcinoma, but had an inverse correlation in melanoma." (PMID 33293474, 2020). "It is known that AnxA1 autocrine signaling by its N-terminal peptide sustains proinvasive properties of melanoma cells." (PMID 30884823, 2019). "ANXA1 was expressed in 97/120 (81 %) of the melanoma samples, with 67/81 (83 %) of primary and 30/39 (77 %) of metastatic melanoma samples positive." (PMID 25594008, 2014). "In our study, we found that protein expression levels of annexin A1 were upregulated, whereas annexin A2 levels were downregulated in A375 melanoma exosomes." (PMID 23056502, 2012). "Annexin A1 has also been shown to amplify the ability of cells to become invasive and to enhance melanoma dissemination." (PMID 23056502, 2012). "Butyrate promotes melanoma invasion by upregulating annexin A1 (ANXA1) and activating the EMT." (PMID 40332093, 2025). "Neutrophil-derived Annexin A1 (AnxA1) contributes to melanoma metastasis." (PMID 40636453, 2025).